KIF14 (kinesin family member 14)
Description:
Microtubule motor protein that binds to microtubules with high affinity through each tubulin heterodimer and has an ATPase activity (By similarity). Plays a role in many processes like cell division, cytokinesis and also in cell proliferation and apoptosis. During cytokinesis, targets to central spindle and midbody through its interaction with PRC1 and CIT respectively. Regulates cell growth through regulation of cell cycle progression and cytokinesis. During cell cycle progression acts through SCF-dependent proteasomal ubiquitin-dependent protein catabolic process which controls CDKN1B degradation, resulting in positive regulation of cyclins, including CCNE1, CCND1 and CCNB1. During late neurogenesis, regulates the cerebellar, cerebral cortex and olfactory bulb development through regulation of apoptosis, cell proliferation and cell division (By similarity). Also is required for chromosome congression and alignment during mitotic cell cycle process. Regulates cell spreading, focal adhesion dynamics, and cell migration through its interaction with RADIL resulting in regulation of RAP1A-mediated inside-out integrin activation by tethering RADIL on microtubules.
Synonyms: KIAA0042; MCPH20; MKS12
Tractability: Antibody: its Gene Ontology location is reachable by antibodies, with high confidence. PROTAC: ubiquitination databases record sites on it.
Target class: Other cytosolic protein
Gene: Protein-coding gene on chromosome 1 (200,551,497 to 200,620,771, reverse strand). Ensembl gene ENSG00000118193.
Subcellular location: Nucleus; Cytoplasm; Cytoplasm, cytoskeleton, spindle; Midbody
Subcellular location (Human Protein Atlas): Cytosol; End piece; Calyx; Connecting piece; Mid piece; Midbody ring; Plasma membrane; Principal piece
Pathways (Reactome):
Signal Transduction: RHO GTPases activate CIT; RND1 GTPase cycle; RND2 GTPase cycle
Gene Ontology:
Molecular function: PDZ domain binding; protein binding; protein kinase binding; ATP binding; ATP hydrolysis activity; microtubule binding; plus-end-directed microtubule motor activity; tubulin binding; microtubule motor activity
Biological process: activation of protein kinase activity; establishment of protein localization; mitotic metaphase chromosome alignment; negative regulation of apoptotic process; negative regulation of integrin activation; positive regulation of cell population proliferation; positive regulation of cytokinesis; proteasome-mediated ubiquitin-dependent protein catabolic process; regulation of cell adhesion; regulation of cell growth; regulation of cell migration; regulation of G1/S transition of mitotic cell cycle; regulation of G2/M transition of mitotic cell cycle; regulation of Rap protein signal transduction; SCF-dependent proteasomal ubiquitin-dependent protein catabolic process; substrate adhesion-dependent cell spreading; cell proliferation in forebrain; cerebellar cortex development; cerebellar granular layer structural organization; cerebellar Purkinje cell layer structural organization; cerebral cortex development; hippocampus development; microtubule depolymerization; negative regulation of neuron apoptotic process; olfactory bulb development; and 5 more
Cellular component: cytoplasm; cytosol; membrane; microtubule; midbody; nucleus; plasma membrane; spindle midzone; kinesin complex; spindle
Genetic constraint (gnomAD): Loss-of-function variants: 49 observed, 95.66 expected, observed/expected ratio (o/e) 0.51, 90% interval 0.41 to 0.65. The upper end of that interval is the gene's LOEUF score, 0.65, which puts it in group 2 of 6, group 1 being the genes least tolerant of losing a copy. Missense variants: 1,201 observed, 1,364.4 expected, observed/expected ratio (o/e) 0.88, 90% interval 0.84 to 0.92. Synonymous variants: 388 observed, 462.76 expected, observed/expected ratio (o/e) 0.84, 90% interval 0.77 to 0.91.
Homologues: Orthologues: chimpanzee KIF14 (99% identical), macaque KIF14 (96% identical), dog KIF14 (79% identical), rabbit KIF14 (75% identical), rat Kif14 (72% identical), mouse Kif14 (72% identical), pig KIF14 (64% identical), tropical clawed frog kif14 (50% identical), zebrafish kif14 (46% identical), Drosophila melanogaster neb (22% identical). Paralogues in human: KIF1B (22% identical), KIF1A (22% identical), KIF16B (22% identical), KIF13B (21% identical), KIF13A (21% identical), KIF1C (19% identical), KIF26B (14% identical), KIF21A (14% identical), KIF21B (14% identical), KIF26A (13% identical), KIF7 (13% identical), CENPE (13% identical), and 29 more.
Diseases named in the same sentence as KIF14 in open-access papers:
KIF14 is named in the same sentence as 79 diseases in open-access papers, as found by Europe PMC text mining. Sharing a sentence is not in itself a finding about the gene and the disease. The quoted sentences say what the papers report.
glioma (26 papers, 2013 to 2025). A benign or malignant brain and spinal cord tumor that arises from glial cells (astrocytes, oligodendrocytes, ependymal cells). "KIF14 is highly expressed in gliomas and is associated with higher mitotic and Ki67 indices, as well as lower patient survival rates." (PMID 39458936, 2024). "Aberrant expression of KIF14 (kinesin-like protein) has been shown in glioma, which is linked with increased aggressiveness." (PMID 34646821, 2021). "In glioma, high KIF14 expression in tissues has been associated with higher pathological grade, and upregulated KIF14 has been observed to predict lower overall survival." (PMID 31823805, 2019). "KIF14 overexpression has also been associated with a poor outcome in lung cancers, ovarian cancers, breast cancers and adult gliomas." (PMID 26933822, 2016). "The lncRNA PAX-interacting protein 1-antisense RNA1 (PAXIP1-AS1) enhances angiogenesis in glioma by recruiting a transcription factor to the KIF14 promotor, which is a prognostic marker in glioma patients as it has been associated with glioma aggressiveness in prior studies." (PMID 32992718, 2020). "The evidence provided by this study supports the stance that the lncRNA PAXIP1-AS1/ETS1/KIF14 axis is implicated in the aggression potential of glioma and may be targeted for the development of therapies." (PMID 31823805, 2019). "Through verification experiments, it was found that lncRNA PAXIP1-AS1 is highly expressed in glioma tissues and cells, accompanied by upregulation of KIF14." (PMID 38967893, 2024). "Overexpression of lncRNA PAXIP1-AS1 enhances the migration, invasion, and angiogenesis of human umbilical vein endothelial cells in glioma by recruiting transcription factor ETS1 to upregulate KIF14 expression." (PMID 38967893, 2024). "Overexpression of PAXIP1-AS1 advances glioma development by recruiting the transcription factor ETS1 to increase KIF14 expression." (PMID 37582104, 2023). "LncRNA PAXIP1-AS1 was identified to boost migration and angiogenesis of glioma by upregulating ETS1-midiated KIF14 expression." (PMID 35440045, 2022). "KIF14 was identified as a likely oncogene in breast, ovarian and lung cancers, as well as retinoblastomas and gliomas." (PMID 33190424, 2021). "CENPE and KIF14 downregulation was shown to potentiate the effects of TZM in reducing glioma cell proliferation." (PMID 34663805, 2021). "To further understand their effects in glioma, we examined the expression of KIF14 in glioma tissues and cells by Western blot analysis." (PMID 31823805, 2019). "The results showed that KIF14 was highly expressed in glioma tissues and cells as compared with the corresponding controls (p < 0.05)." (PMID 31823805, 2019). "In glioma, the abnormal expression of KIF14 has been demonstrated, which is further elevated with increased aggressiveness." (PMID 31823805, 2019). "Then, validation experiments were conducted to confirm a high expression level of lncRNA PAXIP1-AS1 in glioma tissues and cells, accompanied by upregulated KIF14." (PMID 31823805, 2019). "The treatment of oe-PAXIP1-AS1 + sh-ETS1 or sh-KIF14 attenuated the migration and invasion ability of glioma cells (p < 0.05)." (PMID 31823805, 2019). "We note that overexpression of lncRNA PAXIP1-AS1 advances the development of glioma by recruiting the transcription factor ETS1 to increase KIF14 expression." (PMID 31823805, 2019). "The key findings of this study highlighted the potential of the lncRNA PAXIP1-AS1/ETS1/KIF14 axis as a therapeutic target for glioma treatment, due to its role in controlling the migration and invasion of glioma cells and its angiogenesis." (PMID 31823805, 2019). "We and others identified KIF14 as an important oncogene, prognostic indicator, biomarker and therapeutic target in the progression of multiple cancers, including retinoblastoma, glioma, breast, lung, renal, hepatocellular and ovarian cancers]." (PMID 24626475, 2014).
glioma (continued). "Knocking down KIF14 can reduce cell proliferation and invasion capabilities, induce apoptosis, and inhibit glioma growth, suggesting that KIF14 may be a potential target for HGBT treatment." (PMID 39458936, 2024). "KIF14 was proposed as prognostic marker for glioma patients." (PMID 34663805, 2021). "LncRNA PAXIP1-AS1 is located in the glioma cell nucleus, where it could increase the promoter activity of KIF14 through recruitment of the transcription factor ETS1." (PMID 34646821, 2021). "Moreover, combination of stable KIF14 knockdown with TMZ synergize in reducing the proliferation of pediatric high-grade glioma cell lines." (PMID 34663805, 2021). "In terms of glioma, previous studies have shown that overexpression of KIF14 could promote glioma cell migration, invasion and angiogenesis." (PMID 34605738, 2021). "The lncRNA PAXIP1-AS1/ETS1/KIF14 axis could be considered as a target for glioma therapy, because of its contribution to invasion, migration, and angiogenesis in glioma tumors." (PMID 34646821, 2021). "Apart from interfering with cytokinesis, the fraction of cells in G2/M phase was significantly higher in glioma cell lines infected with KIF14-siRNA than in uninfected cells (U251 and U87 cells), indicating that KIF14 silencing induces G2/M phase arrest in glioma cells." (PMID 34495250, 2021). "As a member of LETM1-binding genes, kinesin family member 14 (KIF14), a potential oncogene, exhibited promotive effects on the malignant development of many cancers, including gastric cancer, colorectal cancer and glioma." (PMID 34605738, 2021). "ETS1 promotes angiogenesis by upregulating the expression of KIF14 in glioma." (PMID 33203790, 2020). "Besides, we found that KIF14 was highly expressed in the glioma gene-expression microarray dataset GSE104291." (PMID 31823805, 2019). "Overexpression of lncRNA PAXIP1-AS1 enhanced migration, invasion, and angiogenesis of human umbilical vein endothelial cells in glioma by recruiting the transcription factor ETS1 to upregulate the expression of KIF14, which was further confirmed by accelerated tumor growth in nude mice." (PMID 31823805, 2019). "Therefore, we explored the regulatory mechanisms underlying the putative involvement of the lncRNA PAX-interacting protein 1- antisense RNA1/ETS proto-oncogene 1/kinesin family member 14 (PAXIP1-AS1/ETS1/KIF14) axis in glioma cell invasion and angiogenesis." (PMID 31823805, 2019). "Moreover, KIF14 has been demonstrated as a candidate prognostic marker for outcome in glioma, ovarian cancer and hepatocyte carcinoma patients." (PMID 27128470, 2016). "Contrary to our results, previous studies have shown that KIF14 expression was significantly increased in gastric cancer tissues, hepatocellular carcinoma, glioma, pancreatic adenocarcinoma, and medulloblastoma, suggesting that its precise role may depend on the tumor type and/or context." (PMID 40075652, 2025). "Knockdownof KIF14 by siRNA can inhibit the growth of independent anchorage and induce G2/M arrest, which leads to a decrease in the phosphorylation and activity of Akt, thus inducing apoptosis and cytokinesis failure of glioma cell lines and inhibiting the growth of tumors." (PMID 32546690, 2020). "Moreover, ETS1 upregulated the expression of KIF14 in glioma." (PMID 33203790, 2020). "Thus, a hypothesis that the lncRNA PAXIP1-AS1/ETS1/KIF14 axis has functional relevance in glioma pathology was framed and investigated." (PMID 31823805, 2019). "After calculating the hazard ratio and confidence interval, we observed that 8 hub genes in hub network 1 were related to the poor prognosis of gliomas, including PBK, KIF2C, CENPE, KIF14, MND1, FAM83D, NEIL3, and CDKN3." (PMID 35387222, 2022). "Next, overexpression vectors and shRNAs were delivered to alter the expression of lncRNA PAXIP1-AS1, KIF14, and ETS1 to analyze their effects on glioma progression in vivo and in vitro." (PMID 31823805, 2019).
glioma (continued). "Here, we have demonstrated that lncRNA PAXIP1-AS1 promoted glioma cell migration, invasion and angiogenesis by recruiting transcription factor ETS1 to upregulate KIF14 expression." (PMID 31823805, 2019). "Herein, we examined the expression and functional relevance of lncRNA PAXIP1-AS1 in glioma, which was involved with the ETS1/KIF14 axis." (PMID 31823805, 2019). "Previous studies suggested that KIF14 was increased in multiple cancer including hepatocellular carcinoma (HCC), lung cancer, breast cancer, glioma, laryngeal carcinoma and ovarian cancer." (PMID 28525372, 2017). "We demonstrated that miR-137 and miR-6500-3p exhibit anti-tumor activity in pediatric glioma cell lines by blocking CENPE, KIF14 or NCAPG expression." (PMID 26933822, 2016). "Interestingly, KIF14’s role as a prognostic indicator is also evident in specific brain tumors, such as WNT-subgroup gliomas, where higher KIF14 expression correlates with improved survival." (PMID 40075652, 2025). "In 20 glioma tissues, KIF14 levels were increased compared to non-neoplastic brain tissues and they correlated with the tumor pathological grade, being higher in grade II–IV." (PMID 34663805, 2021). "Specifically, this study provides evidence suggesting that lncRNA PAXIP1-AS1 upregulates the expression of KIF14 by recruiting the transcription factor ETS1, which accelerates the development of glioma as reflected by enhanced glioma cell migration, invasion, and angiogenesis." (PMID 31823805, 2019). "Thus, overexpressed lncRNA PAXIP1-AS1 enhanced glioma cell migration, invasion, and angiogenesis by recruiting transcription factor ETS1 to upregulate KIF14 expression." (PMID 31823805, 2019). "Cell behaviors in glioma could be orchestrated by lncRNA PAXIP1-AS1, due to its mechanistic function in mediating KIF14 via ETS1." (PMID 31823805, 2019). "Furthermore, the results showed that in glioma tissues the expression of lncRNA PAXIP1-AS1 and that of KIF14 were positively correlated (p < 0.05)." (PMID 31823805, 2019). "And, not surprisingly, Kif14 is considered to play a role as an oncogene in cancer types as varied as breast, lung, liver, gastric, colorectal, ovarian, cervical, and prostate cancers in addition to glioma, medulloblastoma, and retinoblastoma." (PMID 33547352, 2021).
breast carcinoma (25 papers, 2012 to 2025). "In breast cancer, high expression of KIF14 can promote breast cancer metastasis and is associated with poor prognosis of breast cancer patients." (PMID 36341437, 2022). "In the other studies in breast cancer, overexpression of KIF11 and KIF14 has been associated with worse overall survival, indicating their potential as prognostic biomarkers." (PMID 40075652, 2025). "For instance, it was found that KIF14 was significantly upregulated by more than 10-fold in breast cancer and that higher expression successfully predicted dismal survival rates and frequent cancer recurrence." (PMID 33995648, 2021). "Recently, KIF14 has been reported as a prognostic biomarker and oncogene in certain carcinomas, including breast cancer, colorectal cancer, gastric cancer, HCC, lung cancer, ovarian cancer, retinoblastoma, and glioblastoma." (PMID 33203790, 2020). "Based on the IHC data, we assessed the association of the expression of HAX1, KIF14, Mieap, and EZR with breast cancer metastasis." (PMID 32679794, 2020). "High expression of KIF5B is observed in breast and skin cancer, and the overexpression of KIF14 promotes the development of retinoblastoma, lung cancer, and breast cancer." (PMID 33585227, 2020). "In breast cancer, an increased level of KIF14 is related to high tumor grade and poor overall survival." (PMID 32679794, 2020). "There is increasing evidence that KIF14 is overexpressed in multiple types of tumors, including hepatocellular carcinoma, lung cancer, breast cancer, etc, implicating its role as an potential oncogene." (PMID 28525372, 2017). "CIT, a serine/threonine-protein kinase, functions together with Kif14 (its expression increased by more than four folds in the TCGA breast cancer samples) in cell division." (PMID 28212608, 2017). "For example, an earlier study led by Corson and Gallie showed that KIF14 mRNA expression was a predictor of grade and outcome in breast cancer." (PMID 27128470, 2016). "There are many candidate genes; CENF, KIF14, DTL, NEK2, CKS1B, ASPM and EXO1 each of which are significantly associated with poor clinical outcome in breast cancer patients." (PMID 25312014, 2014). "The subsequent filtering with the combined p-value <0.005 across 6 datasets, yielded 7 candidate genes ASPM, KIF14, NEK2, DTL, CENPF, CKS1B and EXO1 that are significantly associated with poor clinical outcome of the breast cancer patients." (PMID 24147022, 2013). "For example, several reports have been showed that the increased KIF14 expression is related to a variety of different cancers tumorigenesis and poor prognosis, including retinoblastoma, lung cancer, and even breast cancer." (PMID 23585914, 2013). "Probably, non-genetic factors may account for changes in the expression of these proteins, because, according to TCGA, KIF14, EZR, and SPATA18 genes are very rarely mutated in breast cancer (less than 1%)." (PMID 32679794, 2020). "KIF14 was identified as a candidate oncogene in the 1q minimal region of genomic gain in breast cancer, medulloblastoma, lung cancer, retinoblastoma, and renal cell carcinomas 39 with its overexpression being associated with poorer prognosis in these malignancies." (PMID 33033514, 2020). "In breast cancer, KIF14 expression correlates with proliferation." (PMID 30385851, 2018). "Nevertheless, despite these issues, the activity of KIF14, Mieap, and EZR in torpedo-like structures presents an interest for further understanding mechanisms of invasion–metastasis cascade, and can be a potential marker for predicting the risk of breast cancer metastatic spread." (PMID 32679794, 2020). "Commonality with most of the short-listed genes (CENPF, KIF14, NEK2, CKS1B and ASPM) is their positive association with proliferation marker Ki-67, thereby, indicating their possible role in cell cycle related dysregulations and the resultant proliferation of breast cancer cells." (PMID 24147022, 2013).